SLCO2A1 (solute carrier organic anion transporter family member 2A1)
Description:
Mediates the transport of prostaglandins (PGs, mainly PGE2, PGE1, PGE3, PGF2alpha, PGD2, PGH2) and thromboxanes (thromboxane B2) across the cell membrane. PGs and thromboxanes play fundamental roles in diverse functions such as intraocular pressure, gastric acid secretion, renal salt and water transport, vascular tone, and fever. Plays a role in the clearance of PGs from the circulation through cellular uptake, which allows cytoplasmic oxidation and PG signal termination. PG uptake is dependent upon membrane potential and involves exchange of a monovalent anionic substrate (PGs exist physiologically as an anionic monovalent form) with a stoichiometry of 1:1 for divalent anions or of 1:2 for monovalent anions. Uses lactate, generated by glycolysis, as a counter-substrate to mediate PGE2 influx and efflux. Under nonglycolytic conditions, metabolites other than lactate might serve as counter-substrates. Although the mechanism is not clear, this transporter can function in bidirectional mode. When apically expressed in epithelial cells, it facilitates transcellular transport (also called vectorial release), extracting PG from the apical medium and facilitating transport across the cell toward the basolateral side, whereupon the PG exits the cell by simple diffusion (By similarity). In the renal collecting duct, regulates renal Na+ balance by removing PGE2 from apical medium (PGE2 EP4 receptor is likely localized to the luminal/apical membrane and stimulates Na+ resorption) and transporting it toward the basolateral membrane (where PGE2 EP1 and EP3 receptors inhibit Na+ resorption) (By similarity). Plays a role in endometrium during decidualization, increasing uptake of PGs by decidual cells. Involved in critical events for ovulation. Regulates extracellular PGE2 concentration for follicular development in the ovaries (By similarity). Expressed intracellularly, may contribute to vesicular uptake of newly synthesized intracellular PGs, thereby facilitating exocytotic secretion of PGs without being metabolized (By similarity). Essential core component of the major type of large-conductance anion channel, Maxi-Cl, which plays essential roles in inorganic anion transport, cell volume regulation and release of ATP and glutamate not only in physiological processes but also in pathological processes (By similarity). May contribute to regulate the transport of organic compounds in testis across the blood-testis-barrier (Probable).
Synonyms: PGT; SLC21A2; OATP2A1; MATR1; PHOAD; PHOAR2
Tractability: Small molecule: a structure with a bound ligand is known; it belongs to a druggable protein family. Antibody: UniProt places it where antibodies can reach, with high confidence; its Gene Ontology location is reachable by antibodies, with high confidence; UniProt predicts a signal peptide or a membrane-spanning region. PROTAC: a small molecule that binds it is known.
Target class: Electrochemical transporter; SLC superfamily of solute carriers; SLC21/SLCO family of organic anion transporting polypeptides; Transporter
Safety:
Unwanted effects reported when the protein is acted on. In parentheses: how it was acted on, where the effect was seen, and who reports it.
hyponatremia (source: ClinPGx)
Gene: Protein-coding gene on chromosome 3 (133,932,699 to 134,052,184, reverse strand). Ensembl gene ENSG00000174640.
Subcellular location: Cell membrane; Basal cell membrane; Cytoplasm; Lysosome
Pathways (Reactome):
Disease: Defective SLCO2A1 causes primary, autosomal recessive hypertrophic osteoarthropathy 2 (PHOAR2)
Transport of small molecules: Organic anion transport by SLCO transporters
Gene Ontology:
Molecular function: lipid transporter activity; prostaglandin transmembrane transporter activity; secondary active transmembrane transporter activity; transmembrane transporter activity
Biological process: lipid transport; prostaglandin transport; sodium-independent organic anion transport; transmembrane transport
Cellular component: basal plasma membrane; basolateral plasma membrane; cytoplasm; lysosome; membrane; plasma membrane
Genetic constraint (gnomAD): Loss-of-function variants: 60 observed, 71.79 expected, observed/expected ratio (o/e) 0.84, 90% interval 0.68 to 1.04. The upper end of that interval is the gene's LOEUF score, 1.04, which puts it in group 4 of 6, group 1 being the genes least tolerant of losing a copy. Missense variants: 745 observed, 832.4 expected, observed/expected ratio (o/e) 0.89, 90% interval 0.84 to 0.95. Synonymous variants: 308 observed, 336.3 expected, observed/expected ratio (o/e) 0.92, 90% interval 0.83 to 1.01.
Homologues: Orthologues: chimpanzee SLCO2A1 (99% identical), macaque SLCO2A1 (98% identical), pig SLCO2A1 (88% identical), rabbit SLCO2A1 (87% identical), dog SLCO2A1 (86% identical), mouse Slco2a1 (83% identical), rat Slco2a1 (83% identical), guinea pig SLCO2A1 (82% identical), tropical clawed frog slco2a1 (62% identical), zebrafish slco2a1 (53% identical), Drosophila melanogaster Oatp30B (30% identical). Paralogues in human: SLCO2B1 (42% identical), SLCO3A1 (34% identical), SLCO1C1 (32% identical), SLCO1B3 (32% identical), SLCO1A2 (31% identical), SLCO5A1 (31% identical), SLCO1B1 (30% identical), SLCO4C1 (29% identical), SLCO4A1 (28% identical), SLCO6A1 (22% identical).
Diseases named in the same sentence as SLCO2A1 in open-access papers:
SLCO2A1 is named in the same sentence as 96 diseases in open-access papers, as found by Europe PMC text mining. Sharing a sentence is not in itself a finding about the gene and the disease. The quoted sentences say what the papers report.
primary hypertrophic osteoarthropathy (19 papers, 2015 to 2024). A genetically and clinically heterogeneous inherited disorder characterized by digital clubbing and osteoarthropathy, with variable features of pachydermia, delayed closure of the fontanels, and congenital heart disease. "Whole-exome sequencing has indicated the pathophysiological significance of the SLCO2A1 gene in human; loss-of-function mutations in SLCO2A1 are related to primary hypertrophic osteoarthropathy and pachydermoperiostosis." (PMID 32408168, 2020). "Clinical studies with individuals bearing recessive mutations in SLCO2A1 have demonstrated that SLCO2A1 is a causative gene for primary hypertrophic osteoarthropathy (PHO) and CEAS, in which PGE2 catabolism is defective." (PMID 33166338, 2020). "For example, whole exome sequencing in patients with similar symptoms without previous knowledge of candidate genes led to the identification of WISP 3 and SLCO2A1 as the pathogenic mutations in progressive pseudorheumatoid dysplasia and primary hypertrophic osteoarthropathy." (PMID 34294115, 2021). "Homozygous or compound heterozygous mutations in SLCO2A1 are known to cause not only CEAS but also a subtype of primary hypertrophic osteoarthropathy (PHO)." (PMID 29313109, 2018). "Defective PGT due to loss-of function (LOF) mutations elevates extracellular PGE2 levels and are consequently linked to inflammatory diseases such as Primary Hypertrophic Osteoarthropathy (PHO) and Chronic Enteropathy Associated with SLCO2A1 (CEAS)." (PMID 38783936, 2024). "SLCO2A1 is also a causal gene of primary hypertrophic osteoarthropathy (PHO)." (PMID 29313109, 2018). "Because mutations in the SLCO2A1 gene, encoding a prostaglandin transporter, have been reported to be the pathogenic cause of primary hypertrophic osteoarthropathy (PHO; OMIM 614441), we investigated whether CNSU patients had clinical manifestations of PHO." (PMID 26539716, 2015). "In addition to CEAS, SLCO2A1 defects can cause a subtype of primary hypertrophic osteoarthropathy (PHO), PHO autosomal recessive 2 (PHOAR2) featuring digital clubbing, pachydermia, and periostosis." (PMID 38755710, 2024). "Cyclooxygenase-2 (COX-2) inhibitor has been administered to patients with the loss-of-function mutation of SLCO2A1 presenting with primary hypertrophic osteoarthropathy; however, patients with GI symptoms are not responsive to this treatment." (PMID 36035430, 2022). "In addition, because SLCO2A1 defects also cause another disease primary hypertrophic osteoarthropathy (PHO)/pachydermoperiostosis (PDP), we consulted two CEAS patients to a dermatologist in our hospital and got the answer that there were no characteristic findings of PHO/PDP." (PMID 33166338, 2020). "Primary hypertrophic osteoarthropathy (PHO) is a rare disease related to HPGD and SLCO2A1 gene mutation." (PMID 31878983, 2019).
colon cancer (10 papers, 2007 to 2024). "However, up to now, there was only one SLCO2A1-mutated patient reported to suffer from colon neoplasm." (PMID 31063976, 2019). "SLCO2A1 has been reported to promote the development of colon cancer by PGE2 uptake into the endothelial cells." (PMID 34676211, 2021). "Studies with Slco2a1 knockout mice suggested that SLCO2A1 is involved in promotion of colon cancer, bleomycin-induced fibrosis, and LPS-induced febrile responses." (PMID 35002778, 2021). "We evaluated mice of various Slco2a1 genotypes in a murine model of colon cancer, the adenomatous polyposis (APC) mutant (Apc∆716/+) model." (PMID 29185482, 2017). "Blocking SLCO2A1 has been shown to reduce colon cancer tumorigenesis." (PMID 32103057, 2020). "The role of prostaglandin transporter OATP2A1/SLCO2A1 in colon cancer tumorogenesis is unknown." (PMID 29185482, 2017). "Organic anion-transporting polypeptides (OATPs) are upregulated in various solid tumors, including liver cancer, with SLCO2A1 (OATP2A1) elevated in HCC and liver metastases from colon cancer, while SLCO1B1 expression decreases in liver cancer, showing a reverse trend with cancer grade." (PMID 38534987, 2024). "Interestingly, SLCO2A1, a transporter of the PGE2, is involved in the angiogenesis during wound healing and the development of colon cancer." (PMID 34422812, 2021). "However, no direct co-expression for ABCC4 with these enzymes or SLCO2A1 was observed in our study, which was in contrast to previous data from a colon cancer study." (PMID 30131693, 2018). "How does absence of Slco2a1 affect colon cancer tumorogenesis?" (PMID 29185482, 2017).
Pachydermoperiostosis (9 papers, 2015 to 2023). with prominent pachydermia and minimal-to-absent skeletal changes. "In most cases, PHO was reported as a major clinical hallmark, whereas pachydermoperiostosis was the second most reported phenotype due to SLCO2A1 mutations." (PMID 36833358, 2023). "Another study showed that myelofibrosis is involved in pachydermoperiostosis observed in SLCO2A1-deficient individuals, implying that failure of control of local PGE2 concentration is associated with tissue degeneration." (PMID 25923111, 2015). "Mutations in HPGD gene are responsible for autosomal recessive primary hypertrophic osteoarthropathy 1 (PHOAR1) and mutations in SLCO2A1 gene are responsible for autosomal recessive primary hypertrophic osteoarthropathy 2 (PHOAR2)." (PMID 30352415, 2018). "Two other disease-causing SLCO2A1 mutants, G222R and P219L, which are associated with pachydermoperiostosis in humans, were non-functional in the channel activity." (PMID 34073084, 2021). "As usually happens in patients with mutations in the SLCO2A1 gene, this patient suffered from pachydermoperiostosis (PDP), but no cognitive/neurological clinical manifestations were identified." (PMID 30818802, 2019).
pachydermia (7 papers, 2019 to 2024). "Similarly, it has been observed that the degrees of arthritis, joint involvement, and pachydermia in patients with homozygous SLCO2A1 variants are more pronounced as compared to those of patients having biallelic HPDG variants." (PMID 36833358, 2023). "However, phenotypes such as arthritis, joint involvement, and pachydermia are more prominent in patients homozygous for SLCO2A1 mutations than HPGD homozygous or compound heterozygous-affected individuals." (PMID 36833358, 2023). "However, the degree of joint involvement, pachydermia, and arthritis in affected individuals having homozygous SLCO2A1 mutations seems to be more pronounced than in individuals having HPDG mutations." (PMID 36833358, 2023). "The degree of pachydermia and associated histological alterations have been correlated with serum PGE2 levels and SLCO2A1 genotypes." (PMID 39011225, 2024). "Pachydermia, one of the triad of PHO, were observed in 52% of the reported PHOAR1 cases, which is much lower than those in PHO patients with SLCO2A1 mutations." (PMID 35813463, 2022). "Compared to those with PHOAR2 caused by SLCO2A1 defects, patients with PHOAR1 are six times more likely to be males than females, with clinical features of early-onset hypertrophic osteoarthropathy, milder pachydermia, gastrointestinal symptoms, and lower prevalence of arterial catheters." (PMID 36969274, 2023).
Hyponatremia (6 papers, 2017 to 2025). An abnormally decreased sodium concentration in the blood. "In turn, the individuals with a genetic baseline decrease in the prostaglandin transporter activity (encoded by SLCO2A1) are in the risk group for thiazide-induced hyponatremia." (PMID 37629226, 2023). "We focused on SLCO2A1 (encoding PGT) because augmented renal water reabsorption seemed most relevant to the principal abnormality of hyponatremia from our phenotype studies." (PMID 28783044, 2017).
colorectal cancer (5 papers, 2014 to 2022). A primary or metastatic malignant neoplasm that affects the colon or rectum. "The present study demonstrated that genetic ablation of Slco2a1 strongly enhanced survival and this was associated with a marked suppression in the number of large colorectal cancer polyps." (PMID 29185482, 2017). "Risk estimates for the involvement of polymorphisms in COX-2/HPGD/SLCO2A1/ABCC4 genes in colorectal cancer onset stratified by sex, smoking habits and body mass index." (PMID 24694755, 2014). "Genotype frequencies among cases and controls and risk estimates for the involvement of COX-2/HPGD/SLCO2A1/ABCC4 polymorphisms in colorectal cancer onset." (PMID 24694755, 2014). "Other candidates, PARG and TDGF1, have been associated with cancer regulation; however, the functional role of the candidates HORMAD1, PIGC, NCAM2, INO80D, SLCO2A1, SLC12A1, and METTL19 was unclear in colorectal cancer." (PMID 27383761, 2016).
colitis (4 papers, 2020 to 2023). Inflammation of the colon. "Mice with conditional knockout of SLCO2A1 gene in macrophages were more susceptible to DSS-induced colitis, which is related to the intestinal phenotype of PHO." (PMID 37705574, 2023). "Taking these findings together, it can be considered that the NLRP3 inflammasome in macrophages was autocrinally activated by the elevated concentrations of PGE2, leading to exacerbation of colitis in Slco2a1-deficient mice." (PMID 32184453, 2020). "To investigate whether Slco2a1 deficiency in macrophages is associated with exacerbation of colitis, we developed mice with macrophage-specific deletion of Slco2a1 (Lysozyme M-cre;Slco2a1fl/fl, hereafter referred to as Slco2a1ΔMP)." (PMID 32184453, 2020). "This hypothesis was proven true by administering mice MCC950, a specific inhibitor of the NLRP3 inflammasome, as MCC950 administration reduced the severity of colitis in Slco2a1-deficient mice via suppressing the expression of mature IL-1β and cleaved caspase-1." (PMID 32184453, 2020). "Animal experiments demonstrated that SLCO2A1 deficiency increased PGE2 concentrations in colon tissue, thus resulting in exacerbated colitis." (PMID 37705574, 2023). "To investigate the role of SLCO2A1 in colitis development, we next examined the effects of Slco2a1 deficiency in experimental colitis models of Slco2a1−/− and WT mice established by administering 3.5% DSS in the drinking water for 7 days." (PMID 32184453, 2020). "Therefore, we conducted an unbiased microarray assay to identify mechanisms for the exacerbation of experimental colitis in Slco2a1-knockout mice." (PMID 32184453, 2020). "Therefore, we next explored PGE2 production by Slco2a1-deficient macrophages, which were identified as key players in DSS colitis exacerbation." (PMID 32184453, 2020). "The present study revealed that germline Slco2a1-deficient mice were more susceptible to DSS-induced colitis than WT mice, but did not spontaneously develop enteritis or colitis." (PMID 32184453, 2020). "However, SLCO2A1 protected against gut inflammation in an experimental colitis model." (PMID 32184453, 2020). "Protein levels of mature IL-1β and cleaved caspase-1 were increased in colon tissues of Slco2a1-knockout mice treated with DSS, which led us to hypothesize that NLRP3 inflammasome activation might contribute to the exacerbation of DSS colitis in Slco2a1-deficient mice." (PMID 32184453, 2020). "In summary, Slco2a1 deficiency increased the PGE2 concentration around macrophages, possibly by suppressing PGE2 metabolism, resulting in activation of the NLRP3 inflammasome in macrophages and thus exacerbating intestinal inflammation in an experimental colitis model." (PMID 32184453, 2020). "To assess the inflammasome status in macrophages with genetic Slco2a1 deletion, we isolated colonic lamina propria (LP) macrophages from WT and Slco2a1−/− mice with DSS-induced colitis." (PMID 32184453, 2020). "In support of this, exacerbated colitis in mice lacking Slco2a1 was improved by treatment with the COX inhibitor indomethacin as the concentration of PGE2 around macrophages decreased." (PMID 32184453, 2020).
anemia (3 papers, 2018 to 2025). A reduction in the number of red blood cells, the amount of hemoglobin, and/or the volume of packed red blood cells. "Additionally, severe anemia is more prevalent in the PHO with SLCO2A1 mutation but comparable in the three clinical subtypes." (PMID 40251683, 2025). "Two females aged 34 and 19 years with homozygous pathogenic SLCO2A1 mutations were both without typical PHO symptoms but the elder individual was affected with mild finger clubbing and severe transfusion-dependent anemia." (PMID 30352415, 2018).
Crohn disease (3 papers, 2015 to 2019). A gastrointestinal disorder characterized by chronic inflammation involving all layers of the intestinal wall, noncaseating granulomas affecting the intestinal wall and regional lymph nodes, and transmural fibrosis. "In this study, we identified recessive mutations in the SLCO2A1 gene, encoding a prostaglandin transporter, as causative variants of this disorder by exome sequencing of four families, and showed that this disease is distinct from Crohn’s disease." (PMID 26539716, 2015). "By Sanger sequencing of the coding regions, 11 of 12 other CNSU patients and 2 of 603 patients with a diagnosis of Crohn’s disease were found to have homozygous or compound heterozygous SLCO2A1 mutations." (PMID 26539716, 2015). "It is noteworthy that GI involvement in PHO can mimic other entities including chronic gastritis, peptic ulcer, Crohn’s disease, cryptogenic multifocal ulcerous stenosing enteritis (CMUSE), and chronic enteropathy associated with SLCO2A1 gene (CEAS)." (PMID 31878983, 2019).
diabetes (3 papers, 2015 to 2024). "We hypothesized that inhibition of the prostaglandin transporter (PGT) (SLCO2A1), which mediates the degradation of PGs, would increase blood flow and stimulate vascularization, thereby mitigating peripheral ischemia and accelerating wound healing in diabetes." (PMID 26230411, 2015).
endometriosis (3 papers, 2015 to 2025). The growth of functional endometrial tissue in anatomic sites outside the uterine body. "Indeed, studies with human tissues revealed that expression of PGT in endometrium is modulated during menstrual cycle, and is increased in endometriosis patients, suggesting potentially essential physiological and pathological roles of SLCO2A1 in endometrium in females." (PMID 38755710, 2024).